FOXM1 (forkhead box M1)
Diseases named in the same sentence as FOXM1 in open-access papers (continued):
Sharing a sentence is not in itself a finding about the gene and the disease.
leukemia (24 papers, 2009 to 2025). A malignant (clonal) hematologic disorder, involving hematopoietic stem cells and characterized by the presence of primitive or atypical myeloid or lymphoid cells in the bone marrow and the blood. "Our results revealed new signaling involved in FoxM1 expression and its role in leukemic cells that elucidate cellular mechanisms associated with the development of leukemia and disease progression." (PMID 23110199, 2012). "Of note, Foxm1 loss significantly delayed the relapse of LSCs in MA9 leukemia mouse model." (PMID 32066721, 2020). "We performed homing assay to determine whether Foxm1 loss affected the homing ability of MA9-induced leukemia cells." (PMID 32066721, 2020). "We next determined the role of Foxm1 loss in MA9-induced leukemia in vivo in mice." (PMID 32066721, 2020). "We next evaluated the effects of Foxm1 loss on established MA9-transformed leukemia in vivo." (PMID 32066721, 2020). "Morphological analysis revealed more blast cells in the BM as well as leukemia cell infiltration in the spleens, livers, and lungs of Foxm1 heterozygous AE9a mice." (PMID 37526082, 2023). "Further in-depth investigations are warranted to elucidate the potential significance of combination treatment of NSP-B together with FOXM1 targeting agents in preclinical animal models for the successful treatment of leukemia." (PMID 35847923, 2022). "All together these data confirm that by comparison with normal hematopoietic stem and progenitor cells, FOXM1 appears selectively required for leukemia cell proliferation." (PMID 34711181, 2021). "Taken together, we conclude that MLL-r AML with a high FOXM1 expression is more sensitive to FOXM1 inhibition than other leukemia cell lines." (PMID 32066721, 2020). "Of note, MV4-11, THP-1, and NOMO-1 leukemia cell lines with presence of MLL-fusion genes exhibited high FOXM1 expression compared to leukemia cell lines such as K-562, and Kasumi-3 which lack MLL-fusion genes." (PMID 32066721, 2020). "Of note, inhibition of FOXM1 suppressed growth of primary MA9 leukemia cells in vivo in mice, as evidenced by a lower percentage of human donor cells present in PB cells in FOXM1-specific peptide-treated xenografted mice as compared to PBS-treated mice." (PMID 32066721, 2020). "When the engraftment of primary leukemia cells in vivo reached at approximately 5% in PB in xenografted mice, the mice were treated with FOXM1-specific peptide or PBS for 14 days." (PMID 32066721, 2020). "Here, the authors show that FOXM1 is required for the maintenance of quiescence and self-renewal of leukemia stem cells in MLL-AF9-rearranged acute myeloid leukemia patient and mouse models." (PMID 32066721, 2020). "Decreasing FOXM1 activity in human and murine leukemia cells with WT NPM1 led to decreased clonogenicity and increased apoptosis." (PMID 30089730, 2018). "We did additional experiments using BM MNCs from FLT3-ITD–induced leukemia in FOXM1-overexpressing and control transgenic mice." (PMID 30089730, 2018). "We have also shown chemosensitization using FLT3-ITD leukemia developed in a transgenic FOXM1-overexpressing model." (PMID 30089730, 2018). "FOXM1 is a key transcriptional factor involved in the proliferation of cancer cells including leukemia cells that were very sensitive to both TOPK and MELK inhibitors." (PMID 26933922, 2016). "Although some data have revealed FoxM1 as regulated by Hedgehog and Ras signaling pathways in solid cancer, FoxM1 regulation in leukemia, mainly in chronic leukemia, is poorly understood." (PMID 23110199, 2012). "Loss of Foxm1 impairs LSC function, highlighting its critical role in MLL-rearranged leukemia." (PMID 37526082, 2023). "Additionally, FOXM1 had been found to be required for survival, quiescence and self-renewal of leukemia stem cells (LSCs), which directly binds to β-catenin to decrease its degradation, activating the Wnt/β-catenin signaling pathways." (PMID 37904848, 2023).
leukemia (continued). "However, our recent research has revealed that Foxm1 is also crucial for maintaining the quiescence of leukemia stem cells (LSCs) in the MLL-AF9 mouse model." (PMID 37526082, 2023). "In addition, FOXM1 upregulation stimulates the Wnt/β-catenin signaling crosstalk by directly binding to β-catenin, thereby preserving self-renewal ability of leukemia CSCs." (PMID 35945194, 2022). "Interestingly, this effect was least pronounced in the NPM1 mutant cell line (OCI-AML3), consistent with previous studies suggesting that nuclear export of FOXM1 by mutant NPM1 contributes to the relative chemosensitivity of this leukemia." (PMID 34711181, 2021). "To determine whether Foxm1 deletion delays relapse after chemotherapy in MA9 leukemia mice, we treated cohorts of MA9-Foxm1-CKO and MA9-Foxm1fl/fl recipient mice with DOXO and Ara-C." (PMID 32066721, 2020). "Hou reported that FoxM1 can regulate Nurr1 expression in mouse and human leukemia cells." (PMID 31704909, 2019). "Moreover, our findings demonstrate the need for the development of more specific and potent FOXM1 inhibitors in the treatment of leukemia." (PMID 30089730, 2018). "First, leukemia cell lines with stable knockdown of FOXM1 were generated as previously published." (PMID 30089730, 2018). "We then tested whether the suppression of FOXM1 induced leukaemia-specific cell death in patient-derived pre-B ALL cells and observed significant cytotoxicity at concentrations of 0.5 μmol l−1 thiostrepton." (PMID 25753524, 2015). "In addition, we deleted Foxm1 in vivo by treating mice with tamoxifen after injection of 100,000 leukaemia cells carrying tamoxifen-inducible Cre or an empty vector control." (PMID 25753524, 2015). "Although we observed complete deletion of Foxm1 in vitro, ex vivo deletion and expansion of cell numbers in vivo revealed high levels of Foxm1 by the time of BM harvest from leukaemia-bearing mice, implying proliferative advantage of cells that evaded deletion of Foxm1." (PMID 25753524, 2015). "However, the role of FoxM1, the signaling involved in its activation and its role in leukemia are poorly known." (PMID 23110199, 2012). "Of note, the one leukemia that did not exhibit increased FOXM1 expression following chemotherapy had the highest baseline expression of refractory-associated genes, including FOXM1 and associated cell cycle genes." (PMID 34711181, 2021). "However, we also observed that FOXM1 inhibition induced the differentiation of primary human leukemia cells, as evidenced by presence of significant number of differentiated myeloid cells in BM from FOXM1-specific peptide-treated xenografted mice as compared to PBS-treated mice." (PMID 32066721, 2020). "However, the understanding of the role of FoxM1 drug resistance in leukemia is poorly known." (PMID 23110199, 2012). "CHEK2 is known to interact with several proteins that affect leukemia-specific pathways, such as KMT2D and FOXM1, but this remains to be explored further." (PMID 40335619, 2025). "Moreover, it has been demonstrated that FOXM1 (Forkhead Box M1), a known transcription factor that stimulates cell proliferation in a range of cancer cells, is necessary for the quiescence, self‐renewal, and survival of leukemia stem cells (LSCs) transformed by MLL‐AF9 in vivo." (PMID 39428967, 2024). "Instead, GDA acts at the post-translational level, presumably by promoting the proteasomal degradation of FOXM1 due to abrogated HSP90 chaperone function, as seen in leukemia." (PMID 35794249, 2022). "Here we show that Foxm1 is required for survival, quiescence and self-renewal of MLL-AF9 (MA9)-transformed leukemia stem cells (LSCs) in vivo." (PMID 32066721, 2020). "To further elucidate the role of FOXM1 in human AML cells, we determined the effects of FOXM1 inhibitors on MV4-11, THP-1, and NOMO-1 leukemia cells with expression of MLL-fusion genes." (PMID 32066721, 2020).
leukemia (continued). "Given the putative role of the leukemia-initiating cells (LICs) in mediating relapse, we also explored the effect of chemotherapy on the LIC population in the context of FOXM1 overexpression." (PMID 30089730, 2018). "Ixazomib ameliorates leukemia burden in an orthotopic model of AML, and this correlated with FOXM1 suppression." (PMID 30089730, 2018). "Collectively, these findings indicate that Foxm1 plays a critical role in driving ALL cells proliferation, survival and leukaemia progression." (PMID 25753524, 2015). "Similar to existing data concerning solid tumors, our data suggests that FoxM1 and STAT3 mRNA levels are concomitantly overexpressed in leukemia-resistant K562-R cells." (PMID 23110199, 2012). "In particular, FOXM1 upregulation has been reported in BCR-ABL1+ acute lymphoblastic leukemia (ALL) where its deletion impairs cell proliferation and viability as well as leukemia formation." (PMID 39898030, 2025). "In agreement with our findings in MA9-induced mouse model, inhibition of FOXM1 promoted LSCs to exit from quiescence and significantly induced apoptosis of LSCs but not mature leukemia cells." (PMID 32066721, 2020). "Comparable percentage of YFP+/leukemia cells were detected in BM cells from both recipient mice transplanted with MA9-Foxm1fl/fl or MA9-Foxm1-CKO cells, suggesting that loss of Foxm1 does not affect the homing ability of MA9-induced leukemia cells." (PMID 32066721, 2020). "We showed that Foxm1 loss and chemotherapeutic drugs had a synergistic effect on induction of apoptosis of mouse primary MA9-LSCs but not relatively mature leukemia cells." (PMID 32066721, 2020). "This suggests that doses of ixazomib that suppress FOXM1 and attenuate leukemia disease severity do not disrupt normal hematopoiesis." (PMID 30089730, 2018). "Although FoxM1 has been proposed to be essential for a myriad of solid tumor cancers, the mechanisms that control FoxM1 expression and the role of FoxM1 in leukemia have not been fully elucidated." (PMID 23110199, 2012). "However, the molecular mechanism of the FOXM1/BUB1B regulatory network and the role of Neosetophomone-B (NSP-B) in leukemia remains unclear." (PMID 35847923, 2022). "Taken together, our data suggest that increased expression of Foxm1 likely enhances the self-renewal and survival of MA9 LSCs through multiple molecular pathways including the Wnt/β-catenin pathway, thereby contributing to the maintenance and drug resistance of MA9-induced leukemia." (PMID 32066721, 2020). "However, both β-CATENIN-specific shRNAs barely affect the expression of Foxm1 in the same cells, suggesting that β-CATENIN does not affect FOXM1 expression in MLL-r leukemia cells." (PMID 32066721, 2020).
sarcoma (24 papers, 2009 to 2025). A usually aggressive malignant neoplasm of the soft tissue or bone. "Downregulation of FOXM1 in in vitro and in vivo sarcoma models reduces cell proliferation and sarcomagenesis." (PMID 36551696, 2022). "In fact, they postulate that overexpression of FOXM1 by Hippo effector protein YAP is necessary for tumorigenesis in some sarcomas, based on reduced proliferation seen in a mouse model of UPS after YAP knockdown." (PMID 27732970, 2017). "In that regard, an interesting candidate will be the FoxM1 transcription factor that regulates, as a bulk, most kinetochores genes and which is highly expressed in sarcoma." (PMID 28035071, 2017). "The central role of FOXM1 in the cell cycle, and it's recurring theme of importance in stem cell preferentially activated developmental pathways suggests that targeting FOXM1 is a potential advance in treating sarcoma." (PMID 27074562, 2016). "Current systemic treatment of sarcoma is of limited efficacy and inhibiting FOXM1 represents a potential new strategy." (PMID 27074562, 2016). "It is likely that sarcoma subtypes with a high differentiation score are more likely to be sensitive to therapeutic inhibition of FOXM1." (PMID 27074562, 2016). "YAP suppression in human sarcoma cell lines resulted in decreased proliferation and decreased FOXM1 expression, suggesting a novel role for YAP in co-activating FOXM1-mediated transcription in STS." (PMID 26389076, 2015). "Although 84% of the MFH samples stained positive for FOXM1 (p = 0.02), this marker was also expressed, but to a lesser degree, in other sarcoma subtypes." (PMID 19956606, 2009). "Expression of Foxm1 is elevated in mouse sarcomas that metastasize to the lung and tissue microarray analysis of human MFH correlates overexpression of FOXM1 with metastasis." (PMID 19956606, 2009). "FOXM1 can promote cell cycle progression and pluripotency in sarcoma, accelerating sarcoma growth." (PMID 39736850, 2025). "Forkhead box M1 (FOXM1) is a YAP transcriptional target highly expressed in sarcomas." (PMID 36551696, 2022). "Similar to embryonic carcinoma or neuroblastoma, FOXM1 in UPS could maintain the characteristic undifferentiated state of this sarcoma." (PMID 36551696, 2022). "Importantly, pharmacological FOXM1 inhibition limits tumor size in vivo, implying that FOXM1 can potentially serve as a therapeutic target in sarcomas." (PMID 33445626, 2021). "In addition, it has been reported that disruption of the Hippo pathway promotes FOXM1 expression in sarcoma." (PMID 34117362, 2021). "YAP-mediated proliferation through its target gene FOXM1 could be prevented in sarcoma cell lines and mouse models through the administration of thiostrepton that reduces FOXM1 levels." (PMID 32206112, 2020). "Together, these findings highlight FOXM1 as a potential therapeutic target for some sarcomas." (PMID 27732970, 2017). "A complex involving YAP and the transcription factor TEAD elevates FOXM1 in these sarcoma subtypes." (PMID 27074562, 2016). "Therefore the ontological merit in evaluating FOXM1 as a therapeutic target in sarcoma, especially undifferentiated pleomorphic sarcoma, is apparent." (PMID 27074562, 2016). "Silencing FOXM1 expression suppressed the proliferation of both cancer and sarcoma cell lines." (PMID 27439614, 2016). "FOXM1 expression was found to be increased in a variety of human sarcoma samples." (PMID 26389076, 2015). "In xenograft studies, FOXM1 suppression inhibited sarcoma growth." (PMID 26389076, 2015). "Within the mouse model Foxm1 was elevated in those sarcomas that metastasised to the lung." (PMID 24216705, 2013). "In multiple sarcoma types, YAP expression is elevated through disruptions in the Hippo signaling pathway, and it is known to promote FOXM1 gene expression." (PMID 37686402, 2023).
sarcoma (continued). "Mirroring MNK1/2 silencing, ETC-168 treatment strongly blocks eIF4E phosphorylation and represses expression of sarcoma-driving onco-proteins including E2F1, FOXM1, and WEE1." (PMID 33564073, 2021). "FOXM1 stimulates transcription of pluripotency related genes including SOX2, KLF4, OCT4, and NANOG many of which are important in sarcoma, a disorder of mesenchymal stem cell/ partially committed progenitor cells." (PMID 27074562, 2016). "In these sarcomas i.e. fibrosarcoma, undifferentiated pleomorphic sarcoma and liposarcoma, YAP dependent expression of FOXM1 is necessary for cell proliferation and tumorigenesis." (PMID 27074562, 2016). "A multiple peptide cocktail vaccine (KOC1, FOXM1 and KIF20A) has already been tested in patients with refractory pediatric sarcoma in a phase I study." (PMID 26640950, 2015). "In the human sarcoma cell lines, CA9 was upregulated 18- to 36-fold, whereas FOXM1 remained relatively unchanged or slightly decreased." (PMID 22684860, 2013). "In the mouse sarcoma cell lines, CA9 was upregulated 24- to 49-fold, whereas FOXM1 levels again remained relatively unchanged or decreased slightly." (PMID 22684860, 2013). "Biologically, the activation of FOXM1 by CDK4/6 is critical for CDK4/6-mediated cell cycle entry, suppressing the levels of reactive oxygen species (ROS), and protecting cancer cells (breast, melanoma, sarcoma) from senescence." (PMID 37686402, 2023). "The protein forkhead box M1 (FOXM1), which belongs to the FOX family of transcription factors, is considered to be an independent predictor of poor survival in many cancers and sarcomas, but the prognostic implications and oncogenic roles of FOXM1 in SS are poorly understood." (PMID 27439614, 2016). "Furthermore, multiple peptides cocktail vaccine (KOC1, FOXM1 and KIF20A) has already been tested for the patients with refractory pediatric sarcoma in phase I study." (PMID 26640950, 2015). "Furthermore, FOXM1 was shown to directly interact with the YAP1 transcriptional complex via TEAD1, resulting in the co-regulation of numerous critical proliferation targets that enhance sarcoma progression." (PMID 34831091, 2021). "Likewise, human MFH with high FOXM1 expression correlated with decreased metastasis-free survival compared to sarcomas with low to no FOXM1 expression." (PMID 19956606, 2009). "It will be interesting to examine that possibility and to determine whether FOXM1 and RABL6A act cooperatively to promote tumorigenesis, not only in driving PNF to MPNST transformation but in the malignant progression of other sarcoma types and solid tumors, where both proteins are highly expressed." (PMID 37686402, 2023).